YTHDF1 (YTH N6-methyladenosine RNA binding protein F1)
Diseases named in the same sentence as YTHDF1 in open-access papers (continued):
Sharing a sentence is not in itself a finding about the gene and the disease.
lung cancer (continued). "For example, YTHDF1 promotes the progression of lung cancer by participating in the m6A demethylase the ALKBH5 pathway." (PMID 34026603, 2021). "Studies on nonsmall cell lung cancer (NSCLC) have shown that the high expression of YTHDF1 can promote the development of tumors by promoting protein translation of cyclin E-associated kinase 2 (CDK2), cyclin-dependent kinase 4 (CDK4) and cyclin D1 mRNAs." (PMID 33692959, 2021). "As was previously shown by proteomic analysis of lung carcinoma cells, the knockdown of YTHDF1 led to activation of cell cycle inhibitor p27Kip1 and suppression of cell cycle activator genes encoding CDK2, CDK4 and cyclin D1." (PMID 33317545, 2020). "Therefore, by combining TMT labeling-based proteomic analysis with previous findings, we explored the roles of CDK6 and MAP3K6 in lung cancer development and the relationship between YTHDF1, CDK6, and MAP3K6." (PMID 40278596, 2025). "Therefore, investigating the regulatory mechanisms of YTHDF1 in lung cancer is clinically significant." (PMID 40278596, 2025). "miR-139/145-5p act as upstream regulators of YTHDF1 in the development of lung cancer." (PMID 40278596, 2025). "We next explored the role of YTHDF1 in lung cancer metastasis." (PMID 38342601, 2024). "In addition, the expression of YTHDF1 was analyzed by using the TCGA dataset, which indicated that YTHDF1 was frequently upregulated in lung cancer." (PMID 37259333, 2023). "Furthermore, YTHDF1 depletion has been shown to decelerate the suppressive role of lung cancer cells by m6A methylation-mediated FTH downregulation." (PMID 37259333, 2023). "Furthermore, an RIP assay was executed to examine the association between YTHDF1 and FTH in lung cancer." (PMID 37259333, 2023). "Furthermore, the overexpression of ferritin in YTHDF1-depleted cells partially restored lung cancer cell suppression." (PMID 37259333, 2023). "In addition, the high expression of YTHDF1 in lung cancer patients had a relatively adverse prognosis." (PMID 37259333, 2023). "Importantly, FTH overexpression also can reverse the constraint of YTHDF1 knockdown in lung cancer intracellular iron accumulation." (PMID 37259333, 2023). "The suppression of YTHDF1 could inhibit lung cancer cell proliferation and metastasis by decreasing the expression of FTH." (PMID 37259333, 2023). "In the present study, we demonstrated that YTHDF1 is upregulated in lung carcinoma patients." (PMID 37259333, 2023). "In addition, YTHDF1 also produces a marked effect on lung cancer growth and metastasis by mediating YAP expression and activity." (PMID 34026603, 2021). "In addition, YTHDF1 has also been demonstrated to help tumor cells adapt to hypoxic conditions in lung cancer, while hypoxia‐related molecular events are known to facilitate and support CSCs development." (PMID 34586737, 2021). "YTHDF1 downregulation contributed to inhibited tumor growth of lung cancer in vitro." (PMID 34359836, 2021). "This study suggested that YTHDF1 was related to lung cancer." (PMID 33692959, 2021). "Since lung cancer is the leading cause of cancer related death worldwide, and NSCLC accounts for approximately 85% of all cases, we further characterized the functional roles of YTHDF1 in NSCLC58." (PMID 31653849, 2019). "Thus, we aim to address the consequences of the m6A modification reader YTHDF1 in lung cancer and speculate on the related mechanism." (PMID 37259333, 2023).
lung cancer (continued). "We next explored whether YTHDF1 depletion would induce ferroptosis in lung cancer cells." (PMID 37259333, 2023). "In this study, we first identified the subtle relationship between FTH, ferroptosis and m6A modification in lung cancer cells and found that YTHDF1 could directly promote FTH mRNA translation in an m6A-dependent manner, but there are some limitations in our research." (PMID 37259333, 2023). "Next, the wound-healing and Matrigel-coated Transwell assays were used to assess whether YTHDF1 could affect the migration and invasion of lung cancer cells, indicating that YTHDF1 knockdown markedly reduced the migration and invasion of H1299 and A549 cells in vitro." (PMID 37259333, 2023). "Therefore, we evaluated whether FTH participates with YTHDF1 in promoting lung carcinoma cell proliferation, migration and invasion in our next study." (PMID 37259333, 2023). "Additionally, the copper chelator, ammonium tetrathiomolybdate, increased YTHDF1 levels in A549 adenocarcinoma at low concentrations, suggesting YTHDF1 could promote lung cancer growth." (PMID 33616673, 2021). "This phenomenon suggests that YTHDF1 may govern CSCs in an indirect manner in lung cancer." (PMID 34586737, 2021). "Furthermore, YTHDF1 could regulate lung cancer cells responding to cisplatin-dependent chemotherapy as well as affect the patients’ treatment and prognosis." (PMID 34359836, 2021). "The experimental data indicated that YTHDF1, MAP3K6, and CDK6 were significantly over-expressed in lung cancer compared to adjacent normal tissues (p < 0.05)." (PMID 40278596, 2025). "In lung cancer, METTL3 overexpression facilitates drug resistance and metastasis by promoting the translation of YAP and MALAT1 transcripts in cooperation with YTHDF1/3 reader proteins." (PMID 38966069, 2024). "Then, a Pearson correlation analysis was used to measure the relationship between YTHDF1 and FTH in lung cancer." (PMID 37259333, 2023). "As reported by Jin, YTHDF1 and YTHDF2 interacted competitively with YTHDF3 to module YAP expression in lung cancer in an m6A-independent manner." (PMID 36870954, 2023). "Regarding regulation, YTHDF1 can be targeted by miRNAs, including miR-136-5p in CRC and also miR-1285-3p in lung cancer, where Linc00337 is upregulated and acts an miR-1285-3p sponge enhancing YTHDF1 expression." (PMID 37369946, 2023). "In lung cancer, YTHDF1 increased the translation of the YAP gene and induced metastasis and drug resistance in lung cancer cells." (PMID 35197112, 2022). "Some studies have found that biomarkers such as CLEC3B26 and YTHDF1/YTHDF227 affect the immune microenvironment, and metastasis and prognosis of lung cancer." (PMID 36564433, 2022). "Consistently, we found that YTHDF1 was decreased whereas AKR1C1 was increased by IHC in 100% (6/6) NSCLC patients resistant to platinum based neoadjuvant chemotherapy, whose lung cancer progression were examined by computerized tomography (CT) scan." (PMID 31653849, 2019).
lung cancer (continued). "Therefore, we established Benzo[a]pyrene(B[a]P)-induced bronchial epithelial malignant transformed cells (HBE-P35) to simulate the precancerous lesions of NSCLC and investigated the regulatory axis of YTHDF1 in both HBE-P35 and A549 lung cancer cells." (PMID 40278596, 2025). "Therefore, we conclude that YTHDF1 regulates CDK6 and MAP3K6 through m6A in B[a]P-induced HBE-P35 and A549 cells, providing a potential target for lung cancer treatment." (PMID 40278596, 2025). "We first established B[a]P-induced bronchial epithelial malignant transformed cells (HBE-P35), detected the changes in YTHDF1 and m6A levels in lung cancer and malignant transformed cells, and then used proteomics, MeRIP, and RIP to probe the upstream and downstream regulatory proteins of YTHDF1." (PMID 40278596, 2025). "Next, we analyzed mRNA expression of YTHDF1 in lung cancers and noncancerous lung tissues using TCGA database, and found that it was significantly up-regulated in LUADs and LUSCs compared with control subjects." (PMID 39309428, 2024). "Based on in vitro study, we provided a preliminary discussion on the molecular mechanism of YTHDF1-mediated FTH translation in lung cancer cells, but our present study failed to investigate in vivo." (PMID 37259333, 2023). "It is obvious that YTHDF1 regulates multiple signal pathways, but its exact mechanism on lung cancer has not been fully explored." (PMID 37259333, 2023). "The results indicated that the expression of FTH was positively correlated with YTHDF1 expression in lung cancer patients (p = 0.021), and also confirmed that YTHDF1 might regulate FTH expression in lung cancer patients." (PMID 37259333, 2023). "Furthermore, the relationship between YTHDF1 and FTH in lung cancer was investigated by immunohistochemistry." (PMID 37259333, 2023). "The results of the CCK-8 assay and colony formation assay revealed that, compared with the negative control (NC), YTHDF1 depletion suppressed the growth ability of lung cancer cells." (PMID 37259333, 2023). "Collectively, we found that the overexpression of FTH can restore gene expression and phenotypes induced by knockdown of YTHDF1, suggesting that FTH may be a main target to prevent lung carcinoma." (PMID 37259333, 2023). "YTHDF1 and YTHDF2 may be new prognostic and drug targets related to lung cancer tumor immune microenvironment." (PMID 35069586, 2021). "However, the mRNA level of S100P was not affected by YTHDF1, as judged by RT‐qPCR in the stably YTHDF1‐depleted H460 and A549 lung cancer cells." (PMID 38342601, 2024). "Elevated levels of YTHDF1 and YTHDF2 correlate with a good survival outlook, more tumour‐infiltrating lymphocytes and PD‐L1 down‐regulation in NSCLC patients, suggesting their potential as prognostic markers and therapeutic targets related to the TIME in lung cancer." (PMID 39135292, 2024). "Given the widespread finding that YTHDF1 is upregulated and acts as a prognostic biomarker in lung adenocarcinoma progression, targeting the YTHDF1–m6A–FTH axis could be a promising therapeutic strategy for inhibition of lung cancer occurrence and development." (PMID 37259333, 2023). "In this finding, we further elucidated that m6A YTHDF1 mediates the translation of FTH increased and altered by disorder of METTL3 and, thereby, accelerates tumorigenesis in lung cancer cells, meaning FTH is an essential YTHDF1 target gene in lung cancer, obviously, in an m6A-dependent manner." (PMID 37259333, 2023). "However, the role of YTHDF1 in lung cancer has not been fully investigated." (PMID 37259333, 2023). "While YTHDF1 and YTHDF2 expression promote pancreatic and lung cancer cell proliferation, no equivalent research has to date determined a causal relationship between YTHDF1 or YTHDF2 expression in gliomagenesis." (PMID 32375856, 2020).
non-small cell lung carcinoma (38 papers, 2019 to 2025). A group of at least three distinct histological types of lung cancer, including non-small cell squamous cell carcinoma, adenocarcinoma, and large cell carcinoma. "In non-small cell lung cancer, in order to adapt hypoxia microenvironment, YTHDF1 is down-regulated, which further causes the resistance to cisplatin through regulating the translation of CDK2, CDK4 and cyclin D1." (PMID 35022030, 2022). "Our study identified YTHDF1, a reader protein in the N6-methyladenosine (m6A) modification pathway, as a crucial regulator in non-small cell lung cancer (NSCLC)." (PMID 40251202, 2025). "YTHDF1 is an evolutionarily positively selected high-altitude adaptor gene that is amplified in various cancers, including non-small cell lung cancer (NSCLC)." (PMID 37420298, 2023). "Loading microRNA-376c in extracellular vesicles inhibits properties of non-small cell lung cancer cells by targeting YTHDF1." (PMID 36650570, 2023). "YTHDF1 promotes the proliferation of non-small cell lung cancer (NSCLC) cells by enhancing the translational efficiency of cell cycle regulators CDK2, CDK4 and cyclinD1." (PMID 33928028, 2021). "YTHDF1 as a m6A-binding protein plays a vital role in pathogenesis and hypoxia adaptation of non-small cell lung cancer (NSCLC)." (PMID 34150845, 2021). "The demethylase ALKBH5 can remove the m6A modification of YAP, which results in its reduced expression in the non-small-cell lung carcinoma (NSCLC) through an YTHDF1/2-dependent pathway." (PMID 33926508, 2021). "In non-small-cell lung cancer with high expressions of YTHDF1 and YTHDF2, the densities of four subsets of tumor-infiltrating lymphocytes (TILs; PD-1+, CD8+, Foxp3+, and CD45RO+) were significantly higher." (PMID 34956201, 2021). "A previous study had reported that ALKBH5 suppresses tumor progression in non-small cell lung cancer in a YTHDF1-dependent manner." (PMID 34079761, 2021). "Moreover, the interaction between LncRNA DLGAP1 antisense RNA 2 (DLGAP1-AS2) and YTHDF1 has been established to involve in non-small cell lung cancer." (PMID 37365581, 2023). "In addition, a recent finding by our group was that, under normoxic conditions, YTHDF1 is highly expressed in non-small-cell lung cancer cancerous tissues and cell lines to promote cell proliferation via increasing cell-cycle-related factor expression." (PMID 36338714, 2022). "In addition, YTHDF1 promoted non-small cell lung cancer cell proliferation through regulating the translational efficiency of CDK2, CDK4, and cyclin D1." (PMID 33726814, 2021). "In addition, recent finding by our group found that, under normoxic conditions, YTHDF1 is highly expressed in non-small cell lung cancer cancerous tissues and cell lines to promote cell proliferation via increasing cell-cycle related factor expression." (PMID 33611339, 2021). "Moreover, METTL3 induces non-small cell lung cancer (NSCLC) drug resistance and metastasis by promoting Yes-associated protein (YAP) mRNA translation via a m6A -YTHDF1/3/eIF3b-dependent mechanism." (PMID 33015074, 2020). "In non-small cell lung cancer (NSCLC), METTL3 enhances the stability of the lncRNA DLGAP1 antisense RNA 2 (DLGAP1-AS2), which interacts with YTHDF1 and promotes c-MYC mRNA stability via m6A modification." (PMID 41373022, 2025). "After evaluating YTHDF1’s role in advancing tumor cell cycle progression, we examined its known targets, CDK2 and CDK4, in non-small cell lung cancer using RNA Binding Protein Immunoprecipitation Assay (RIP)." (PMID 40251202, 2025). "In non-small cell lung cancer, METTL3 can recruit YTHDF1/3 and eIF3b to form translation initiation complex, thus promoting the translation of YAP." (PMID 35022030, 2022). "According to a recent study, YTHDF1 and YTHDF2 induced inflammation in the TIME in non-small-cell lung cancer." (PMID 36091006, 2022).
non-small cell lung carcinoma (continued). "We examine the expression of YTHDF1, YTHDF2, CD8, CD4, and FOXP3 to identify their prognostic or predictive role for PD-1/PD-L1 inhibitor in non-small cell lung cancer (NSCLC)." (PMID 36479088, 2022). "METTL3 promoted YAP translation by recruiting YTHDF1/3 and eIF3b, and increased YAP expression by the MALAT1/miR-1914-3p axis, leading to drug resistance and metastasis in non-small-cell lung carcinoma (NSCLC)." (PMID 35164788, 2022). "In non-small cell lung cancer (NSCLC), YTHDF1 was reported to promote cancer cell proliferation and tumor progression by regulating the translational efficiency of CDK2, CDK4, and cyclin D192." (PMID 33795663, 2021). "In non-small cell lung cancer (NSCLC), YTHDF1 is identified as a hypoxia adaptor, whose depletion inhibits tumor progression by regulating translation efficacy." (PMID 32733807, 2020). "Recently research revealed that YTHDF1 involved in stability and degradation of multiple LncRNAs, such as LncRNA HCP5 and LncRNA DLGAP1-AS2, thus participating in regulating the progression of esophageal squamous cell carcinoma and non-small cell lung cancer, respectively." (PMID 37365581, 2023). "Our findings suggest that YTHDF1 does not enhance prostate cancer progression through the m6A-modified KEAP1 and Nrf2 axis, as observed in non-small cell lung cancer, highlighting its context-dependent function across different cancer types." (PMID 40251202, 2025).